BRCA1 (BRCA1 DNA repair associated)
Diseases named in the same sentence as BRCA1 in open-access papers (continued):
Sharing a sentence is not in itself a finding about the gene and the disease.
ovarian carcinoma (continued). "One of the most well-known examples is that, a large fraction of hereditary breast cancer, ovarian cancer, and prostate cancer, which are accounted for by BRCA1 and BRCA2 mutations, which are pivotal genes in HR150." (PMID 33299637, 2020). "In the USA and Europe, the detection of BRCA1/2 mutation has become an important screening tool for high-risk populations of ovarian cancer." (PMID 32356124, 2020). "Patients with ovarian cancer or a germline BRCA1 mutation are more prone to have a different proportion of lactobacilli in cervicovaginal microbiome (<50% of species present in the healthy controls)." (PMID 32133297, 2020). "The Thai Gynecologic Cancer Society is aware of the increasing role of PARPi in treatment of ovarian cancer, so this study was conducted among tertiary centers for cancer care in Thailand to determine the BRCA1/2 mutation status in Thai patients with EOC." (PMID 32856869, 2020). "Gronwald and colleagues case-control study did not observe a significant association between coffee consumption and ovarian cancer risk (OR 0.7, 95%CI 0.4,1.3) among 348 women with BRCA1 pathogenic germline gene variant." (PMID 32165993, 2020). "The French guidelines by INCa recommend annual clinical pelvic examination as screening for ovarian cancer in BRCA1 and BRCA2 mutation carriers." (PMID 32655641, 2020). "Risk-reducing salpingo-oophorectomy is the standard of care for ovarian cancer risk management in BRCA1/2 carriers." (PMID 33408585, 2020). "Among women with BRCA1/2 pathogenic germline gene variants, there is insufficient evidence for recommendations related to dietary habits or weight management and ovarian cancer risk." (PMID 32165993, 2020). "Previous studies reported that the restoration of homology-dependent recombination (HDR) function by somatic reversion of germline BRCA1/2 mutations confers platinum and PARPi resistance in ovarian cancer." (PMID 32226530, 2020). "In 2016, Rucaparib was granted an accelerated approval for the treatment of germline or somatic BRCA1/2-mutated advanced ovarian carcinomas, following multiple chemotherapy treatments." (PMID 33015058, 2020). "We assessed the associations between population-based polygenic risk scores (PRS) for breast (BC) or epithelial ovarian cancer (EOC) with cancer risks for BRCA1 and BRCA2 pathogenic variant carriers." (PMID 32665703, 2020). "The FDA has subsequently approved olaparib for frontline maintenance treatment in women with platinum-responsive ovarian cancer and BRCA1/2 mutation." (PMID 33036656, 2020). "Previous cohort studies have determined that BRCA1/2 mutations are associated with improved long-term survival in patients with ovarian cancer." (PMID 33575207, 2020). "If we omit the mucinous ovarian carcinoma group from entire cohort, the rate of BRCA1 mutation in Vietnamese patients with ovarian carcinoma should be 10.4% (8 out of 77 patients)." (PMID 32856862, 2020). "A large proportion of breast and ovarian cancer predisposition remains unexplained: analysis of genes other than BRCA1 and BRCA2 is needed." (PMID 32756499, 2020). "Nowadays, clinical trials have confirmed that PARPi as first-line or second-line maintenance therapy significantly increase progression-free survival in ovarian cancer patients with a BRCA1/2 mutation." (PMID 32183851, 2020). "In 2016, rucaparib was approved for advanced ovarian cancer with both germline and somatic BRCA1/2 mutations." (PMID 32029455, 2020). "It is known that BRCA1 carriers have a 44% risk of developing ovarian cancer, and there is a 17% risk for BRCA2 carriers." (PMID 32069831, 2020). "Ten percent to 15% of breast and ovarian cancer patients carry germline mutations in HR genes BRCA1 and BRCA2." (PMID 32029455, 2020).
ovarian carcinoma (continued). "Studies in the Norwegian population have shown that 1675delA and 1135insA account for one-third of hereditary breast cancer ovarian cancer, while 816delGT and 3347delAG account for 68% of Norwegian BRCA1 mutation carriers." (PMID 32356124, 2020). "The aim of this study was to determine the pathogenicity of the BRCA1 c.5407-25T>A variant found in 20 families from Norway, France and United States with suspected hereditary breast and ovarian cancer." (PMID 32203205, 2020). "The very first clinical trials demonstrated the efficacy of the PARP inhibitor olaparib in breast and ovarian cancer patients carrying germline mutations in BRCA1/2, thus supporting the rationale for synthetic lethality." (PMID 32029455, 2020). "Ovarian cancer incidence increases slowly from approximately 35 years onwards in patients with BRCA1-and from around 50 years onwards in BRCA2-mutations." (PMID 32655641, 2020). "In December 2014, the PARP inhibitor, Olaparib, was approved by the European Medicines Agency (EMA) and the US Food and Drug Administration (FDA), after another drug for BRCA1/2 mutation-positive ovarian cancer." (PMID 33327492, 2020). "One way to guarantee 100% test rates for all patients with ovarian cancer upon diagnosis would be to use “reflex” (i.e., guaranteed) tumour BRCA1/2 mutation testing as part of the pathology department work-up." (PMID 33123697, 2020). "RAD52 is another therapeutic target in breast and ovarian cancer because its depletion is synthetically lethal to cells BRCA2 or BRCA1/PALB2 deficient." (PMID 32932697, 2020). "In a meta-analysis of published studies, the estimated mean cumulative risk for breast and ovarian cancers by 70 years of age for BRCA1 mutation carriers were 57% and 40%, respectively, while carriers of BRCA2 mutation had a risk of 49% and 18%, respectively." (PMID 32733560, 2020). "A recent clinical trial (SOLO-1) compared olaparib versus placebo in BRCA1/2 mutation carriers with newly diagnosed ovarian cancer after response (CR/PR) to platinum-based chemotherapy." (PMID 32833070, 2020). "The breast and ovarian cancers from BRCA1/2 germline mutation carriers show a unique responsiveness to PARP-inhibition and it was suggested that they express distinctive phenotype, which they share with some sporadic breast and ovarian cancers." (PMID 32164626, 2020). "Poly (ADP ribose) polymerase (PARP) inhibitors (PARPi) are approved targeted therapeutics for breast and ovarian cancers bearing a germline BRCA1/2 mutation." (PMID 31863638, 2020). "Increasing numbers of studies have demonstrated that BRCA1 mutations increase the risk of ovarian cancer." (PMID 32762026, 2020). "We found NIH-OVCAR3 cells were 5-fold more sensitive to carboplatin than the 12 ovarian cancer cell lines, which was comparable to the ovarian cancer cells with homozygous mutations in BRCA1." (PMID 32709004, 2020). "Alternative second-hit mechanisms, such as somatic inactivating point mutations, have been described in a small minority of BRCA1-associated breast and ovarian cancers." (PMID 32481735, 2020). "The PARPi talazoparib increases the number of peritoneal CD8+ T cells and natural killer cells and increases production of interferon (IFN)-γ and tumor necrosis factor–α (TNF)- α in a BRCA1-mutated ovarian cancer xenograft model." (PMID 32778095, 2020). "In breast/ovaries cancer‐prone families, the risk for malformations was multiplied by 2.4 [1.2‐4.5] in case of a BRCA1 mutation." (PMID 30785647, 2020). "The discriminative models with serum tumor markers and BRCA1/2 mutation status were constructed for ovarian cancer detection and patient stratification." (PMID 30972954, 2019).
ovarian carcinoma (continued). "In an intriguing study using genetically engineered mice, this interaction between NRF2 and BRCA1 has been proposed to explain why BRCA1 deficiency results in an increased incidence of breast or ovarian cancers." (PMID 35582567, 2019). "Pathogenic germline mutations in BRCA1 and BRCA2 (BRCA1/2) account for the majority of hereditary breast and/or ovarian cancers worldwide." (PMID 31528241, 2019). "The estimated penetrance of BRCA1 mutation carriers by age 70 was 65% for BC and 45% for ovarian cancer, and the corresponding rates of BRCA2 mutation carriers were 45% and 11%." (PMID 30940775, 2019). "These are mainly used as a screening panel to evaluate the hereditary risk of developing specific tumors, e.g., BRCA-1, -2-driven breast and ovarian cancers." (PMID 35582724, 2019). "Little is known about the genetic predisposition to breast and ovarian cancer among the Chilean population, in particular genetic predisposition beyond BRCA1 and BRCA2 mutations." (PMID 31125277, 2019). "Genetic testing for BRCA1/2 mutations has been proved to be a key step in the risk assessment, prognosis, treatment, and prevention of ovarian cancer." (PMID 30972954, 2019). "Highly penetrant variants of BRCA1/2 genes are involved in hereditary predisposition to breast and ovarian cancer." (PMID 30832263, 2019). "A relative deficiency in TILs was also detected in BRCA2-mutated ovarian cancer when compared to BRCA1-mutated tumors." (PMID 31549213, 2019). "The pooled prevalence of BRCA1 mutation among hereditary breast and/ or ovarian cancer was 12% (95% CI: 4–21%)." (PMID 30898109, 2019). "Administering olaparib PARP (poly (ADP-ribose) polymerase) inhibitor, developed for BRCA1/2 mutated ovarian cancer, in combination with TMZ has shown promising results for treating relapsed glioblastoma patients in a phase I clinical trial (NCT01390571)." (PMID 32082376, 2019). "The crosstalk between mTORC2 and BRCA1 arising from their protein interaction is important to understand breast and ovarian cancer susceptibility and improve treatment options based on a patient’s BRCA1 mutation status." (PMID 31771139, 2019). "BRCA1/2, a cancer highly susceptibility gene, has been found in breast and ovarian cancer as mutation carriers widely." (PMID 31577767, 2019). "This mutation is common in patients with ovarian cancer, in which the overall frequency of mutations in BRCA1/BRCA2 is 28%, which is mainly attributable to this founder effect." (PMID 31545835, 2019). "Recent estimates have assessed that women who inherit a mutation in BRCA1 have a chance of 72% (95% confidence interval (CI), 65–79%) of developing BC and of 44% (95% CI, 36–53%) of developing ovarian cancer (OC) in their lifetime." (PMID 30832263, 2019). "CCNE1 amplification is mutually exclusive with BRCA1/2 mutations and correlates with cyclin E1 protein expression in ovarian cancer." (PMID 30665374, 2019). "This study aimed to comprehensively investigate serum tumor markers and BRCA1/2 germline mutations and analyze their associations with ovarian cancer." (PMID 30972954, 2019). "Lastly, BRIP1, which interacts with and is necessary for the function of BRCA1, is a tumour suppressor, and loss-of-function germline mutations increase the risk of breast and ovarian cancers." (PMID 31870430, 2019). "PARPis have become a mainstay for treatment of certain malignancies, especially breast and ovarian cancers, because they can selectively target tumor cells with BRCA1/2 mutation or HR deficiency." (PMID 31001476, 2019). "Germline and somatic BRCA1/2 mutations have been widely studied in breast and ovarian carcinomas as they have been found to enhance the risk for disease progression." (PMID 31577767, 2019). "Analogous to the mutations in BRCA1 discussed previously, this hypermethylation silences expression to inhibit BRCA1 function, driving genomic instability in ovarian cancers." (PMID 30646939, 2019).
ovarian carcinoma (continued). "Recently, screening BRCA1/2 mutations has been applied as a companion diagnostic test guiding clinical medication for ovarian cancer patients." (PMID 30972954, 2019). "For patients with the BRCA1 mutation, the cumulative risk of ovarian cancer at 70 years of age is 39%." (PMID 31915530, 2019). "In the past, prophylactic surgery was only intended for women at high risk of ovarian cancer, such as those with BRCA1/2 gene mutation." (PMID 30362670, 2019). "We aimed to assess the role of deleterious BARD1 germline variants in BC/OC predisposition in a sample of 4920 BRCA1/2-negative female BC/OC index patients of the German Consortium for Hereditary Breast and Ovarian Cancer (GC-HBOC)." (PMID 31036035, 2019). "With the advancement of precision medicine and targeted therapy, detection of BRCA1/2 mutations in blood and/or tumor tissues of patients with breast and ovarian cancer will help select targeted drugs and chemotherapy regimens and better assess prognosis." (PMID 30968603, 2019). "PARP inhibitors offer an important potential treatment for patients with BRCA1/2-mutated breast and ovarian cancers, but clinical studies excluded patients with central nervous system (CNS) metastases, including LC." (PMID 31815182, 2019). "With the introduction of Olaparib treatment for BRCA-deficient recurrent ovarian cancer, testing for somatic and/or germline mutations in BRCA1/2 genes in tumor tissues became essential for treatment decisions." (PMID 31029168, 2019). "Individuals harboring BRCA1/2 germline mutations have high lifetime risks of breast and ovarian cancer." (PMID 31528241, 2019). "Deleterious mutations in Breast Cancer 1 (BRCA1) are associated with an increased risk of breast and ovarian cancer." (PMID 31771139, 2019). "The BARD1 gene (MIM# 601593) was identified in 1996 as the result of a yeast two-hybrid screen for proteins that interact with the breast and ovarian cancer associated BRCA1 protein." (PMID 31803232, 2019). "BRCA1 deficiency results in genomic instability and individual’s susceptibility to breast and ovarian cancer." (PMID 31023256, 2019). "These are normally rescued by homologous recombination (HR), but, in cells with suboptimal HR, PARP inhibition leads to genomic instability and cell death, a phenomenon currently exploited in the therapy of ovarian cancers in BRCA1/2 mutation carriers." (PMID 31329989, 2019). "Constitutional BRCA1 methylation due to cis-acting germline genetic variants is associated with a high risk of breast and ovarian cancer." (PMID 31225507, 2019). "Olaparib is the first PARP1 and PARP2 inhibitor approved for treatment of refractory ovarian cancer harboring BRCA1 or BRCA2 mutation." (PMID 31554189, 2019). "In 2003, Antoniou associated the presence of BRCA1 mutation with a 39% risk for developing ovarian cancer." (PMID 31416275, 2019). "One study showed that 54% of women with ovarian cancer and BRCA1 mutation were diagnosed before the age of 50 years, unusually diagnosed before the age of 40 years, and rarely before 30 years." (PMID 30362670, 2019). "It has been estimated that only 6% of BRCA1/2 mutation carriers in the general population have been identified and a recent study found fewer than one-in-five at-risk breast or ovarian cancer patients have undergone genetic testing." (PMID 31083288, 2019). "In this regard, we have shown that single nucleotide polymorphisms (SNPs) in genes from the base excision repair (BER) pathway can modify breast or ovarian cancer susceptibility in BRCA1 and BRCA2 mutation carriers." (PMID 30747491, 2019). "It has been reported that ovarian cancer patients with BRCA1/2 mutations had significantly more bulky lymph nodes than patients with wild type BRCA1/2." (PMID 30972954, 2019). "Lastly, a majority of breast and ovarian cancer specimens from carriers showed classical signs of BRCA1-mutated tumors." (PMID 31683985, 2019).
ovarian carcinoma (continued). "BRCA1 (Breast Cancer Type 1 Susceptibility gene) is a risk factor gene that alteration in its protein cause in susceptibility to breast or ovarian cancer." (PMID 30806067, 2019). "The first strategy utilizes the synthetic lethality targeting another remaining DNA repair pathway, e.g. by poly (ADP‐ribose) polymerase inhibitors for treating BRCA1/2‐mutated ovarian cancers." (PMID 31115163, 2019). "If both breast and ovarian cancer are diagnosed in the family, the probability of carrying a germline BRCA1 or 2 mutations is 60% (95% CI 50%‐68%)." (PMID 30821131, 2019). "Recent studies have found that BRCA1/2 somatic mutations can also be detected in tumor tissues of breast or ovarian cancer (George, Banerjee, & Kaye, 2017; Moschetta, George, Kaye, & Banerjee, 2016)." (PMID 30968603, 2019). "Poly ADP‐ribose polymerase (PARP) inhibitors are novel targeted drugs, which have recently been approved to treat advanced ovarian cancer patients carrying BRCA1/2 mutations." (PMID 30972954, 2019). "The efficacy of PARP-inhibitors has been well established for breast and ovarian cancers with germline BRCA1/2 mutations." (PMID 31242618, 2019). "Familial cancers other than breast and ovarian cancer were also associated with mutations of the BRCA1 and BRCA2 genes." (PMID 30622657, 2019). "BRCA1/2 pathogenic (P) and likely pathogenic (LP) germline variants are frequent among patients with ovarian carcinoma." (PMID 30606148, 2019). "A potential BRCA1 point mutation located at 43047665 on region 2 band 1 of the long arm of chromosome 17 was assigned to test an ovarian cancer cell line, SNU251." (PMID 30783107, 2019). "Precise estimates of risk by age for breast or ovarian cancer in the carriers of path_BRCA1 variants are important when selecting if and when to undertake PBSO or PBM." (PMID 30678073, 2019). "For BRCA1, the assessed average risk of breast and ovarian cancers ranges from 57 to 65% and 20 to 50%, respectively; for BRCA2, the risk ranges from 35 to 57% and 5 to 23%, respectively." (PMID 31336956, 2019). "Compared to the normal population, BRCA1 mutation carriers have an estimated 44% risk of developing ovarian cancer by age 70, while this risk is up to 27% for BRCA2 mutant individuals." (PMID 30813239, 2019). "Approximately 15% of epithelial ovarian cancers display mutation or loss of BRCA1 or BRCA2, leading to susceptibility to DNA damaging agents." (PMID 31366178, 2019). "Earlier studies evaluating exclusively ovarian cancer patients found a frequency of 11 to 15% germline pathogenic variants in BRCA1 or BRCA2 among epithelial ovarian cancer patients." (PMID 30606148, 2019). "Herein, using traditional epidemiologic and MR methods, we conducted analyses of height and BMI and their association with ovarian cancer risk in the Consortium of Investigators for the Modifiers of BRCA1/2 (CIMBA) with 22,588 participants." (PMID 31213659, 2019). "More than one-fifth of ovarian carcinomas (about 23%) have hereditary susceptibility and germline mutations of BRCA1 and BRCA2 tumor suppressor genes; in particular contribute to 65–85% of these cases." (PMID 31608277, 2019). "The PARPi olaparib (Lynparza, AstraZeneca) has recently been approved for the treatment of ovarian cancers with BRCA1/2 mutations." (PMID 30736840, 2019). "Carbohydrate antigen 125 showed a good performance in ovarian cancer detection as a single marker (AUC = 0.799), while a panel of eight markers showed a good performance in BRCA1 mutation detection with an AUC value of 0.974." (PMID 30972954, 2019). "In around 18% of ovarian cancer patients, it is possible to identify germline mutations in BRCA1 and BRCA2, especially in those with high-grade serous carcinoma." (PMID 31130614, 2019). "In 1990, risk reduction surgery for epithelial ovarian cancer began to be implemented in patients with mutations in BRCA1 and BRCA2." (PMID 31182132, 2019).